KRAS (KRas proto-oncogene, GTPase)
Diseases named in the same sentence as KRAS in open-access papers (continued):
Sharing a sentence is not in itself a finding about the gene and the disease.
liver cancer (31 papers, 2014 to 2026). An epithelial or non-epithelial malignant neoplasm that arises from the liver. "Other studies have reported a similar mutation rate of around 7% in liver cancer, suggesting that KRAS mutations are typically present in fewer than 10% of HCC cases." (PMID 40344393, 2025). "The EGFR downstream effector RAS is a major oncogenic factor for human cancer, and KRAS mutation is the most frequent isoform among RAS mutations in liver cancer patients." (PMID 38791872, 2024). "In liver cancer, activating mutations in KRAS and NRAS are found considerably more frequently than in HRAS." (PMID 26799184, 2016). "KRAS is mutated in ∼7% of liver cancers in human but Ras signaling is ubiquitously activated in HCC." (PMID 24633177, 2014). "KRAS wildtype liver cancer PDOs are sensitive to the inhibition of EGFR-family blockers, whereas KRAS-mutant liver cancer PDOs showed intrinsic resistance." (PMID 39195202, 2024). "Liver cancer organoids (n=7) were also subjected to targeted therapies (KRAS, MET and KIT targeting)." (PMID 33816288, 2021). "G2M checkpoint and KRAS signaling pathway have been proved to play an important role in the progression and development of liver cancer." (PMID 34123827, 2021). "Gene set enrichment analysis (GSEA) revealed upregulation of several oncogenic pathways upon SETD2 loss, including the KRAS transcriptional signature, the PTEN-loss transcriptional signature, and PRC2-repressed targets identified in liver cancer, and malignant peripheral nerve sheath tumors (MPNST)." (PMID 36810256, 2023). "However, mutations in KRAS lead to hyperactivation of the RAS/MAPK signaling pathway, driving uncontrolled cell proliferation and contributing to the development of pancreatic, colorectal, lung, and liver cancers." (PMID 40344393, 2025). "As for the limitations of the current study, although the EGFR downstream effector RAS is a major proto-oncogene for human cancer, the RAS mutation is not very prevalent in patients with liver cancers, with 7% of patients having KRAS mutations and 4% of patients having HRAS mutations." (PMID 38791872, 2024). "Taken together, these results indicate that FBXL6 activates the oncogenic KRAS/MEK/ERK axis, promoting mTOR signaling activation, which leads to the carcinogenesis and development of liver cancer." (PMID 38124228, 2023). "Interact with KRAS protein to inhibit ERK signaling, leading to the suppression of liver cancer cell growth." (PMID 34888249, 2021). "Given that NPM1 is already a therapeutic target in hematopoietic cancers, our findings suggest that targeting NPM1 could also benefit patients with WNT-driven solid tumors, such as KRAS-mutant CRC and hepatic cancers, which remain challenging to treat." (PMID 41413654, 2026). "However, in contrast to other cancer types, so far only three studies have identified and experimentally proved target genes of miR-622 in liver cancer (i.e., mitogen-activated protein 4 kinase 4 (MAP4K4), CXC chemokine receptor 4 (CXCR4), and kirsten rat sarcoma (KRAS)." (PMID 33803354, 2021).
metastatic carcinoma (31 papers, 2011 to 2025). A carcinoma which has spread from the original site of growth to another anatomic site. "Few NMP organoids displayed enriched EMT, TGF-beta signaling, and KRAS signaling up pathways, which seemingly contradicts their associations with invasive tumor features typically observed in more aggressive, metastatic cancers." (PMID 38619751, 2024). "Special attention is devoted to mutated KRAS inhibitors, which probably represent the first dream come true in anti-metastatic cancer therapy of pharmacology researchers and open the way to potentially very broad therapeutic indications." (PMID 37627201, 2023). "To investigate the effect of the centrifugation protocol on the ctDNA fraction, we quantified the KRAS-mutated tDNA and ctDNA in spiked samples from healthy volunteers and KRAS-mutated metastatic cancer patients, respectively." (PMID 30935089, 2019). "In summary, we employed our IVS approach on T-cell PBL subsets from six metastatic cancer patients that harbored KRAS mutation in their tumor." (PMID 30683863, 2019). "Although somatic mutation in codons 12 and 13 is the dominating kind of KRAS genetic alteration, the genetic background of KRAS mutations harbors a high diversity across different cancer types, especially in the metastatic cancer tissues." (PMID 30406144, 2018). "Another study on type 1 ovarian cancer demonstrated that KRAS mutations are associated with poor prognosis in metastatic cancer." (PMID 30509235, 2018). "KRAS mutation pattern is highly diverse among different cancer types and is associated with the survival of patients with metastatic cancers." (PMID 30406144, 2018). "This condition is usually driven by oncogenic KRAS point mutations and evolves into a highly aggressive metastatic carcinoma due to secondary gene mutations and unbalanced expression of genes involved in the specific signaling pathways." (PMID 24878567, 2014). "In this paper we demonstrate that mutational analysis of KRAS can be used diagnostically to more definitively determine the site of origin of a metastatic carcinoma—in this instance a metastatic pancreatic adenocarcinoma to the lung." (PMID 23119210, 2012). "We demonstrate that the mutational analysis of KRAS can be useful to help determine the site of origin of a metastatic carcinoma to the lung in a case in which the morphological and immunohistochemical findings were not definitive." (PMID 23119210, 2012). "In EDTA tubes, KRAS-mutated ctRNA could only be detected in the platelets (CPPlat_P) in 3 out of 4 KRAS-mutated metastatic cancer patients." (PMID 30935089, 2019). "Next, the same number of samples were collected from KRAS-mutated metastatic cancer patients." (PMID 30935089, 2019). "Moreover, KRAS mutation is highly correlated with the overall survival of patients with metastatic cancer." (PMID 30406144, 2018). "Moreover, KRAS mutation is strongly associated with the poor survival of metastatic cancers." (PMID 30406144, 2018). "Clinical studies have demonstrated the antitumor efficacy of covalent KRAS G12C inhibitors in treating advanced/metastatic cancers." (PMID 40304209, 2025). "This suggests that KRAS inhibitors would be effective at constraining the growth cycles of even the most degenerate cells, slowing the progress of even advanced metastatic cancers." (PMID 41446211, 2025).
metastatic carcinoma (continued). "For instance, we found that KRAS was located in an H3K36me3-enriched contact domain in both primary and metastatic cancer cells." (PMID 34348759, 2021). "An H3K9me3-enriched contact domain in primary cancer cells alongside this KRAS contact domain was divided into two contact domains enriched with H3K27me3 and H3K36me3 in metastatic cancer cells." (PMID 34348759, 2021). "Notwithstanding these limitations, our results and those reported for other cancer systems suggest that the combined use of epigenetic drugs with agents that target KRAS or its effector pathways can provide a more effective treatment for metastatic cancer." (PMID 26158412, 2015). "KRAS is located on chromosome 12p—the only chromosomal region in which a statistically significant difference was observed between human primary and metastatic cancer cells." (PMID 22113502, 2011). "Importantly, in a cohort of metastatic cancer patients, KRAS mutations were associated with lack of benefit upon everolimus therapy." (PMID 27602501, 2016).
cutaneous melanoma (29 papers, 2005 to 2025). A primary melanoma arising from atypical melanocytes in the skin. "An integrative analysis was conducted to investigate the role of KRAS-associated signaling pathways in the pathogenesis and clinical outcomes of skin cutaneous melanoma (SKCM)." (PMID 40607411, 2025). "An important consideration is the prevalence of BRAF mutations (particularly V600E) in cutaneous melanoma and its potential interplay with the KRAS-associated pathways investigated here." (PMID 40607411, 2025). "It is important to acknowledge that direct activating mutations in KRAS are relatively infrequent in cutaneous melanoma (<5% in TCGA) compared to BRAF or NRAS mutations." (PMID 40607411, 2025). "We identified BRAF V600E (11/25; 44%) as the most commonly mutated gene, followed by NRAS (2/25; 8%), and KRAS (1/25; 4%) in cutaneous melanomas." (PMID 34102999, 2021). "(C) Estimated IC50 and its uncertainty for skin cutaneous melanoma cell lines tested with the immunomodulatory drug lenalidomide, which showed significant association with KRAS copy number alteration in the ANOVA test." (PMID 33274713, 2020). "Although the overall mutation frequency of KRAS in cutaneous melanoma may be less pronounced than that of BRAF or NRAS, the current findings reinforce the concept that KRAS pathway activation is sufficiently relevant to warrant deeper examination." (PMID 40607411, 2025). "This is consistent to current literature that BRAF, HRAS, KRAS or KIT mutations occur rarely in meningeal MCs and are more commonly observed in cutaneous melanoma." (PMID 41324772, 2025). "NRAS mutations occur in ∼20% of human cutaneous melanomas, while HRAS and KRAS mutations are rare in this disease." (PMID 28497782, 2017). "We also found that there were 206 genes that negatively correlated with HRAS expression significantly overlapped with genes positively correlated with KRAS/NRAS in cutaneous melanoma." (PMID 29349077, 2017). "Looking beyond combinations involving mutant EGFR or KRAS, we found that BRAF mutations in skin cutaneous melanoma (SKCM) were negatively associated with NRAS." (PMID 26047463, 2015). "In addition, the C918 (MUM-2B) cell line has an identical STR profile to the cutaneous melanoma C8161 cell line driven by KRAS." (PMID 34249699, 2021). "Comparing the mutational landscape of brain metastases to that of cutaneous melanomas in the SKCM-TCGA dataset, KRAS was the most significantly enriched driver gene in our dataset, mutated in 8% (4/50) vs 2% (7/358) in the entire SCKM-TCGA collection (p = 0.0227, logistic regression Wald t test)." (PMID 33024263, 2021). "Few studies have focused on the transcriptional level of RAS isoforms (KRAS, NRAS, and HRAS) in cutaneous melanoma." (PMID 29349077, 2017). "On the other hand, the ANOVA model detected the KRAS copy number alteration as a resistance biomarker for lenalidomide (immunomodulatory drug) partial sensitivity in skin cutaneous melanoma (SKCM), whilst not detected by our Bayesian approach." (PMID 33274713, 2020). "According to the report, cutaneous melanoma can be classified into four subtypes: mutant BRAF; mutant NRAS; mutant NF1; and the triple-wild-type, which is characterized by a lack of hot-spot BRAF, N/H/KRAS, or NF1 mutations." (PMID 32028967, 2020). "No KRAS amplification has been previously reported in cutaneous MM, indicating that the carcinogenesis of MM-MCT differs from that of primary cutaneous melanomas." (PMID 33670958, 2021).
cutaneous melanoma (continued). "Our data indicated that HRAS mRNA expression, but not KRAS or NRAS, was correlated with prognosis in cutaneous melanoma." (PMID 29349077, 2017).
endometrioid carcinoma (29 papers, 2010 to 2026). "Molecular studies indicate that adenomyosis may constitute a clonal disease harboring somatic driver mutations shared with endometrioid carcinoma, including KRAS mutations and alterations in the PI3K-AKT-mTOR signaling pathway." (PMID 41909345, 2026). "Interestingly, another murine model with floxed alleles of PTEN and KRAS developed high-grade endometrioid carcinoma when exposed to adenovirus encoding for Cre-recombinase regardless of the tissue type targeted (ovarian surface or oviductal epithelium)." (PMID 25971410, 2015). "Interestingly, PTEN silencing and KRAS mutation originating from ovarian surface epithelium generated endometrioid carcinoma, suggesting that different cellular origins with identical genetic manipulations can give rise to distinct cancer histotypes." (PMID 25971410, 2015). "The predominant histological subtype is endometrioid carcinoma, harboring frequent mutations in PTEN (52–78%), PIK3CA (36–52%), KRAS (15–43%), ARID1A (25–48%), and CTNNB1 (23–24%)." (PMID 34172714, 2021). "In endometrioid carcinoma, PTEN mutations are associated with other mutations found in KRAS proto-oncogene, Catenin Beta 1 (CTNNB1), and PIK3CA genes and microsatellite instability, which results in short DNA sequence alterations and its ultimate replication." (PMID 34322276, 2019). "employed a 4-gene panel (CTNNB1, PTEN, KRAS, and PIK3CA) to analyze paired plasma and tumor tissues from 48 cases of endometrioid carcinoma." (PMID 40860812, 2025).